CD44 (CD44 molecule (IN blood group))
Diseases named in the same sentence as CD44 in open-access papers (continued):
Sharing a sentence is not in itself a finding about the gene and the disease.
cancer (continued). "CD44 is one of the most commonly used marker of CSCs that functions essentially as a cell–cell adhesion protein with a key role in the invasion and metastasis of cancer." (PMID 33071648, 2020). "CD44 is another common marker to identify CSCs in various cancer types, similar to CD133 and EpCAM." (PMID 32391048, 2020). "Therefore, we assume that the inducible acquisition of CD44 and its consequences account for the mechanism by which cancer cells reduce PI3Kα inhibition and maintain AKT/mTOR activation." (PMID 33024087, 2020). "Among all the 37 patients who tested positive for CTCs, the expression of CD44+, a common surface marker for CSCs in many cancers including HCC, was observed in all the stages of HCC, indicating that CTCs with these three markers had a cancer stemness phenotype." (PMID 32610709, 2020). "CD44 binds to hyaluronic acid and with low affinity to heparan sulfate, fibronectin, and collagen It is overexpressed in several cell types, including cancer stem cells." (PMID 33321819, 2020). "In order to sense, remodel and degrade the ECM, matrix receptors such as CD44, integrins or discoidin domain receptors contribute to formation of invasive structures called invadosomes (or invadopodia), allowing invasion of cancer cells and metastasis formation." (PMID 32984031, 2020). "This heterogenic cancer cell population exhibits a complex expression pattern of both differentiated and stem like-related markers such as CD44, a transmembrane glycoprotein that is involved in a series of biological functions and was shown to be overexpressed in GBM and GICs." (PMID 31936544, 2020). "The CD44+/CD24- subpopulation of cancer cells was determined under 6-methoxymellein." (PMID 32977636, 2020). "In the future study, cancer-specific anti-CD44 mAbs may also be developed that can reduce the adverse effects of traditional antibody therapy." (PMID 33000243, 2020). "The histological tissue morphology after two days ex vivo corresponded to the in vivo situation: slices maintained expression of the cancer stem cell (CSC) marker CD44, a necrotic and hypoxic center, as well as an oxic rim with proliferating, BrdU positive cells." (PMID 32560230, 2020). "However, we did not observe down-regulation of other stem cell markers (CD133 and Lgr5), suggesting that both MUC5AC and CD44 have a positive role in maintaining a specific subset of the cancer stem cell population." (PMID 32098629, 2020). "Based on data from the present study, the expression of CD133, rather than CD44, more closely associated with the resistance of cancer cells to anticancer drug." (PMID 32849878, 2020). "Indeed, our previous study revealed that CD44-positive cancer stem-like cells in HNSCC produced various immune suppressive cytokines and enhanced the regulatory T-cell response compared with CD44-negative cells." (PMID 33299117, 2020). "Our data showed that CD44 clustering could promote BrCas malignancy and disruption of CD44 clustering could dramatically inhibit cancer cell migration and invasion." (PMID 33292278, 2020). "Moreover, it was found that cancer cells that survive chemotherapeutic approaches in TNBC patients were of CD44+, CD24–, and high ALDH1 phenotype and showed more improved mammosphere-forming capacity." (PMID 32391048, 2020). "Indeed, we describe, the role of CD44, integrins and DDRs - notably in invadosomes and metastasis formation - in cancer cells and CAFs." (PMID 32984031, 2020). "CD44 is involved in the regulation of diverse vital signaling pathways that modulate cancer proliferation, invasion, metastasis and therapy-resistance, and it is also modulated by a variety of molecules in cancer cells." (PMID 33303029, 2020).
cancer (continued). "Molecules detected on the GSCs included those associated with the cancer stem cell phenotype (CD24, CD44 and CD90), as well as widely expressed cell surface molecules, such as major histocompatibility complex (MHC) class I (and β2‐microglobulin), CD71 and CD98, as expected." (PMID 31784984, 2020). "It is widely accepted that CD44+ cells may be fractionated from heterogeneous single-cell-prepared cancer cells via CD44 specific antibody labeling accompanied by the flow cytometry arrangement." (PMID 32280305, 2020). "In addition, increased CD44 expression and enhanced sphere formation were observed, which suggest increased stemness in cancer cells." (PMID 33172177, 2020). "Finally, the very small tumors stemming from astro-mesenchymal GSCs expressed mainly ASCL1 and a small population of CD44-expressing cancer cells." (PMID 32641768, 2020). "PAA decreased CD44+/CD24−-expressing subpopulation of cancer cells from 47.5% to 21.3%." (PMID 33202749, 2020). "Still, the role of the CD44 variants, v4 and v7, in cancer progression has not been evaluated in detail and requires further investigation." (PMID 32759798, 2020). "Lastly, thanks to the free carboxylic groups in the polymer backbone, HA-based NPs can be further chemically conjugated with an aptamer or other specific ligands in order to obtain dual/multi-targeted NPs which can increase selectivity and efficacy against CD44+ cancer cells." (PMID 32183027, 2020). "In several cancers isoform switching via alternative splicing of CD44 is frequently observed." (PMID 32984308, 2020). "CD44 is one of the genes tightly correlated withgastric cancer." (PMID 31376327, 2020). "In order to increase the binding affinity selectively for the surface of cancer cells, the nanoparticles were non-covalently conjugated to hyaluronic acid (HA), a natural biopolymer, which was found to mediate the targeting recognition of CD44 over-expressing cancer cells." (PMID 31906398, 2020). "Although the expressions of CD44 and CD133 in cancer cells likely associate with the resistances to radiotherapy, chemotherapy, and various stresses, the different significance between CD44 and CD133 has not yet been well understood." (PMID 32849878, 2020). "Interestingly, we found that lower expression of miR-16 in the serum of cancer patients correlated with high expression of its CD44 target protein." (PMID 33224883, 2020). "The regulatory mechanisms of TSG6 and CD44 in cancer metastasis still have to be investigated." (PMID 31548612, 2020). "Also, CD44 is involved in activating various oncogenic events in cancer tissues through activation of signaling pathways such as PI3K/ AKT and RhoGTPase." (PMID 32922663, 2020). "However, most of the studies were conducted in a CD44 antibody-mediated cross-linking manner, so a model that naturally mimics the in vivo clustering of CD44 is urgently needed for cancer study." (PMID 33292278, 2020). "Podoplanin and CD44 are transmembrane glycoproteins involved in inflammation and cancer." (PMID 33003440, 2020). "CD44 usually promotes progression through metastasis, but there are cases where it may serve to anchor the cancer cells to the extracellular matrix and abolishing that ability would likely be detrimental." (PMID 33203146, 2020). "CAFs also improve the adhesion and migration of CRC through upregulation of CD44 in cancer cells." (PMID 32984031, 2020). "Interestingly, the expression of CD44, an osteopontin receptor which is considered a stemness marker in several kinds of cancers, was also reduced in RUNT-KO cells." (PMID 32204402, 2020). "Numerous studies demonstrate CD44 to be a potential therapeutic target among various cancers." (PMID 33303029, 2020). "Antibodies to CD44 are being investigated for cancer therapy." (PMID 33303029, 2020). "Importantly, CD44 is one of the most studied markers of cancer-initiating cell (CIC), with a key function in the maintenance of CIC-associated properties in several solid tumors." (PMID 33081391, 2020).
cancer (continued). "The phenomenon observed in a variety of cancer types that differential expression of CD44 between tumors and corresponding normal counterparts might potently indicate that CD44 plays essential roles in tumorigenesis." (PMID 33303029, 2020). "CD44+ cancer cells show an increase in EMT and in invasion, correlated with poor prognosis." (PMID 32984031, 2020). "However, little is known about the mechanisms involved or related to cancer progression when CD44 undergoes proteolytic cleavage to CD44-ICD." (PMID 33062960, 2020). "CD44 has been considered as a cancer stem cell marker in various tumors." (PMID 33030522, 2020). "Interventions involving cell surface receptors, such as CD44 and several integrins that interact with activated macrophages at sites of inflammation, stimulates cell adhesion and migration, consequently, manipulating cancer and the process of metastasis." (PMID 33163298, 2020). "CD44 can be a promising candidate for predicting the prognosis of cancer patients." (PMID 33303029, 2020). "However, as a protein that increases cell motility and invasion of cancer cells, the role of cell surface adhesion protein CD44 in the formation of filopodia has been minimally studied." (PMID 32679746, 2020). "This study suggests that the targeting approach using HA may offer a valuable tool for the treatment of CD44+ cancer cells." (PMID 33120945, 2020). "Interaction between HA and CD44 mediates adhesion of cancer cells to PMCs and this interaction could potentially be targeted by pharmacologic intervention." (PMID 32780245, 2020). "These miRNAs function in OSCC mainly through modulating the expression of proteins related to cancer stem cells (augmentation of CD44, c-Myc, and Oct-4), drug resistance (upregulation of P-gp and MRP1), and EMT (increase in BMI1 and MMP9 expression and loss of E-cadherin)." (PMID 32547936, 2020). "As the important relationship between cancer cells and their microenvironment becomes increasingly evident, we sought to investigate CD44 as a regulator of inflammatory cytokines within TNBC, through interactions with its ligand, hyaluronan (HA), and subsequent effects on the TME." (PMID 32455980, 2020). "On the other hand, BRCA2 correlated with CD44 in both types of cancer." (PMID 32610620, 2020). "Previous studies have demonstrated that the CD44 is not only a biomarker but also plays critical roles in the maintenance of CSCs, the resistance to various therapies/stresses, and the metastasis of cancer cells." (PMID 32849878, 2020). "Moreover, CD44-mediated signaling interacts with other well-known pro-tumorigenic pathways and oncogenes during cancer development, such as signal transducer and activator of transcription 3 (STAT3)." (PMID 33335857, 2020). "In addition, BT-20 cancer cell line with overexpression of CD44 and MCF-7 cancer cell line with low CD44 expression were used to confirm the selective binding affinity of HACSLA NPs to the HA receptors." (PMID 32151062, 2020). "Interestingly, HAS2 knockdown within cancer stem-like (CD44+/CD24−) MDA-MB-231 BoM cells has been shown to reduce both the number and growth of metastatic lesions in vivo." (PMID 32455980, 2020). "Another function of this protein, which may be important for driving cancer cells in the bone marrow niche, is that CD44 can also bind CXCR4, which is crucial in retaining HSC in the niche, and might be important for cancer cells as well." (PMID 32527062, 2020). "The same CD44 staining patterns were also seen in SUM1315 cancer cells grown on the hydrogels." (PMID 32736579, 2020). "The effects of HA on cancer cells may be mediated through its receptor CD44, which triggers a cascade of signal transduction increases, including increases in PI3K, Cyclin D1 and CDK4." (PMID 32517712, 2020). "CD44, the main receptor for HA, is a well-accepted molecular marker for cancer stem cells." (PMID 33292278, 2020).
cancer (continued). "The association of miRNA-relatedsingle nucleotide polymorphism (SNP) rs8193, locatedwithin 3 ́UTR of CD44 gene, has not been studied ingastric cancer of Iranian population." (PMID 31376327, 2020). "This supports the complex role of CD44 in cancer progression." (PMID 33203146, 2020). "The CD44–HA interactions may, therefore, be exploited in clinical analyses and point-of-care diagnostics for cancer, particularly if computational methods are used to process the data." (PMID 32604896, 2020). "The keygenes involved in the development of cancer includethe oncogenes and tumor suppressor genes, contributingto DNA repair and apoptosis mechanisms, among whichK-Ras, Myc and CD44 are the most important genes thathave been proven to be associated with gastrointestinalcancers." (PMID 31376327, 2020). "CD44 is a transmembrane glycoprotein which is expressed on the cell surface of many cancer cells." (PMID 33050539, 2020). "CD44 is a HA binding molecule which is not highly endocytic and many cancers (as well as immune cells) express variants of CD44 and have abundant pericellular HA." (PMID 32429122, 2020). "Moreover, compared to the NF-treated cells, the expression of cancer stem cell (CSC) markers CD44, CD133, OCT-4 and SOX2, was significantly upregulated in the CF group." (PMID 32754302, 2020). "Indeed, increased expression of CD44 has been observed in trastuzumab resistant gastric and breast cancer cells, as well as in paclitaxel resistant ovarian cancer cells." (PMID 32252293, 2020). "The adhesion molecule CD44 is known as a cancer stem cell marker." (PMID 30781816, 2019). "Furthermore, the BEP seems to inhibit cancer stemness property since the treatment of MDA-MB-231 cells with BEP mitigated colony formation while it simultaneously inhibited stemness-related (CD44 and BMI-1) gene expressions." (PMID 30691094, 2019). "Additionally, recent findings demonstrate that CTC clusters are enriched for cells with cancer stem cell-like features, whereby intercellular homotypic interactions between the cancer stem cell marker CD44 molecules enhance cluster formation." (PMID 31623163, 2019). "Further study we found that Ezh2 could increase the population of cancer stem cells by regulating Nanog, Sox2, CD44." (PMID 30621625, 2019). "However, when we investigated the size of CD44+CD24− cancer stem-like subpopulation, we observed its significant downregulation." (PMID 30952903, 2019). "Indeed, in ovarian cancers cells, TGF-β induces TG2 expression with consequent stimulation of EMT and cancer stem cell phenotype (CD44+)." (PMID 30691081, 2019). "These NPs could selectively target cancer cells by CD44 endocytosis and could have an anti-cancer effect after laser irradiation." (PMID 31266194, 2019). "Interestingly, all the CD44-positive cancer cells were also LSD1 positive, strongly suggesting an association of CSCs with LSD1 expression." (PMID 31627418, 2019). "This may be attributed to the presence of drug-resistant cancer stem cells (CSCs), which are characterized by the presence of CD44." (PMID 31569404, 2019). "Through CD44-mediated endocytosis, loaded Dox was selectively delivered into the cancer cell." (PMID 31262049, 2019). "Moreover, in recent studies, it was further verified that higher CD44 levels allow the cancer to acquire more malignant abilities, and patients with higher levels of CD44 exhibited a shorter survival time 11-13." (PMID 31528214, 2019). "In addition, CD44 and HLA-DRB5 which are directly interacted with HLA-A are known to be implicated by interferon signals in different cancers." (PMID 31856847, 2019). "Moreover, cancer stemness related genes such as CD44, CD133, LGR5, LSD1, OCT4, Sox2 and Sox9 were co-upregulated with LETM1 in A549 cells." (PMID 31500591, 2019). "In addition, recent evidence suggests that CD44 plays an important role in cancer progression because it is capable of facilitating the colonization and metastasis of cancer stem cells." (PMID 30631039, 2019).
cancer (continued). "CD44 was first described as a cell surface marker for cancer precursor cells and exceedingly used as a reliable marker for the identification and isolation of cancer stem cells in different solid tumors." (PMID 31341476, 2019). "Moreover, the CS‐E degradation products strongly stimulate CD44 proteolysis, thereby increasing the CD44‐dependent migration of cancer cells." (PMID 30637950, 2019). "Furthermore, blocking of the CD44–HA interactions between cells but also between cells and EVs can offer new treatment options for cancer." (PMID 30909497, 2019). "It is reported that knockdown of CD44 could lead to the promoted differentiation of cancer stem cells." (PMID 30646947, 2019). "Consequently, it is possible to design therapeutic drugs to target JNK/c-Jun-regulated miR-21 for the treatment of HA/CD44-mediated cancer." (PMID 31293964, 2019). "Upregulated CAF-derived versican can subsequently enhance cancer cell motility and invasion by activating the nuclear factor-κB (NF-κB) signaling pathway and inducing the expressions of CD44, MMP-9, and hyaluronan-mediated motility receptor (HMMR) in the surrounding tumor microenvironment." (PMID 30568223, 2019). "CD44, as a cancer stem cell marker, also plays a pivotal role in chemoresistance." (PMID 31497537, 2019). "The mechanism of CD44 action has been studied extensively in cancer cells." (PMID 31331331, 2019). "CD44 is a cancer stem cell biomarker and Oct-4 and ALDHA1 are stem cell biomarkers." (PMID 31360301, 2019). "Additionally, recent studies have been directed towards CD44-ICD as the main regulator of metastasis in cancer cells through its interaction with transcription factors that regulate expression of genes involved in metastasis." (PMID 31331331, 2019). "CD44 is a common surface marker for CSCs in many cancers including HCC22." (PMID 31819089, 2019). "CD44 is a transmembrane protein and an important regulator of cancer metastasis, and isoform switch of CD44 through incorporating additional variable exons to the extracellular juxtamembrane region is frequently observed during cancer progression." (PMID 31416894, 2019). "The obtained nanogel could kill CD44-targeted HCT-116 cancer cells by delivering GrB into the cytosol of these cells." (PMID 30943985, 2019). "CD44 is one of the main cell surface candidates in cancer stem cells detection and isolation." (PMID 30992079, 2019). "For example, peroxidase activity mimicking nanoparticles, coated with hyaluronic acid (HA), could be used to identify the CD44 overexpressing cancer cells by merely performing a peroxidase reaction." (PMID 30805331, 2019). "For example, HA binding to CD44 promotes Nanog association with DROSHA/p68 microprocessor complex resulting in the upregulation of miR-21 and downregulation of PDCD4 (a tumor suppressor protein) in cancer cells." (PMID 31293964, 2019). "CD44 is a cancer stem marker that seems to induce chemoresistance." (PMID 31205468, 2019). "Additionally, CTC evaluation of mice with PDX tumors with obASCs demonstrated a trend of an increased percentage of human cells enriched for the cancer stem cell marker CD44+CD24− compared to mice with control tumors and tumors with shLeptin obASCs." (PMID 31118047, 2019). "Due to the great capability of HA to target CD44-over-expressing cancer cells, HA-based nanomaterials used in PTT and MHT could accumulate in CD44-over-expressing cancer cells and, subsequently, elicit an anti-cancer effect." (PMID 31266194, 2019). "Further results from immunoblot suggest that CHTOP knockdown not only decreased the protein expressions of two representative surface markers of cancer stem cell (CD44 and ALDH1) but also inhibited the protein expressions of two important transcriptional makers of cancer stem cell (SOX-2 and NANOG)." (PMID 30910850, 2019). "CD44+/CD90+ cells have been identified as a unique population of cancer cells that may be required for the regulation of chemo- and radioresistance through PI3K and mTOR signaling." (PMID 31288154, 2019).